FOXP3 (forkhead box P3)
Diseases named in the same sentence as FOXP3 in open-access papers (continued):
Sharing a sentence is not in itself a finding about the gene and the disease.
malaria (continued). "On the other hand, pre-patent filariasis exacerbates malaria severity through immunosuppression of IFN-γ and initiation of activation of CD4 + CD25 + FoxP3+ T-regulatory cells." (PMID 26377900, 2015). "In the setting of malaria, TNFR2+ Tregs have previously been shown to have higher FOXP3 expression and enhanced suppressive function." (PMID 26182204, 2015). "Very few splenic CD4+Foxp3+ T cells expressed IFN-γ in naïve or malaria-infected WT or WSX-1−/− mice and there was only a transient difference in the frequencies and numbers of CD4+Foxp3+ IFN-γ+ cells in WT and WSX-1−/− mice on day 9 of infection." (PMID 23593003, 2013). "Flow cytometric analysis also showed a significant increase on CD4+CD25+FoxP3+ T cells producing IFN-γ (P<0.0001), IL-17 (P = 0.0020), TGF-β (P<0.0001) and IL-10 (P<0.0001) in malaria-infected individuals." (PMID 20224778, 2010). "Phenotypic characterization revealed that Treg cells from severe malaria cases express high levels of TNFRII and constitute a subset of regulatory cells that express high levels of Foxp3 and appear to exert strong immunosuppressive function." (PMID 20442856, 2010). "CD4+CD25+TNFRII+ T cells were found to express higher levels of Foxp3 than CD4+CD25+TNFRII− T cells, consistent with our earlier observations on TNFRII+ and TNFRII− Treg cells from malaria-exposed individuals." (PMID 19390618, 2009). "The exact role of T-bet+Foxp3+ Tregs in suppressing effector CD4+ T cell responses during malaria has not yet been resolved." (PMID 30915078, 2019). "Although earlier studies on the role of CD4+Foxp3+ Tregs in immunity to malaria were not conclusive, recent findings in mice infected with Plasmodium chabaudi AS or P. yoelii support the notion that Tregs suppress Th1 as well as Tfh cell responses." (PMID 30915078, 2019). "The PD1+CTLA4+ T cells in our malaria patients were clearly distinct from natural Tregs as they did not express Foxp3 or CD25, nor were they CD49b+LAG3+, which are recently identified markers for Tr1 cells." (PMID 27802341, 2016). "Next, we analyzed the intracellular expression of Foxp3 during the first infection to detect natural Tregs, defined as CD4+CD25highFoxp3+ cells and reported to regulate the immune response in malaria." (PMID 24465641, 2014). "While the proportion of CD4+CD25high was higher in the Fulani ethnic group at the peak of malaria transmission season (p = 0.03), no clear pattern emerged for T regulatory cells expressing FoxP3+ and CD127low." (PMID 22283984, 2012). "Some reports indicate that expansion of CD4+CD25+Foxp3+ during murine malaria did not prevent murine CM." (PMID 21439091, 2011). "Moreover, we have identified a population of FOXP3−, CD45RO+, CD4+ T cells which co-produce IL-10 and IFN-γ and which are more prevalent in children with uncomplicated malaria than in those with severe disease." (PMID 19343213, 2009). "The differences between the two groups were suggested to be due to a functional deficit in regulatory T cells, as reflected by lower expression of TGFβ, TGFβRs, CTLA4, and FOXP3 genes in Fulani compared with Mossi ethnic group or European donors not exposed to malaria." (PMID 22283984, 2012). "Thus, immune response tends to become more towards immuno-suppressive with lethal malaria parasite with higher numbers of CD4+ICOS+Foxp3+regulatory T cells whereas with the non-lethal parasite no significant CD4+ICOS+Foxp3+regulatory T cell population was observed." (PMID 35109868, 2022). "Finally, transwell experiments showed that induction of Foxp3 expression, and specifically the generation of Foxp3hi as opposed to Foxp3int CD4 T cells, can be mediated by soluble parasite components smaller than 20 nm and thus likely distinct from the malaria pigment hemozoin." (PMID 24822053, 2014).
malaria (continued). "Increased FOXP3 mRNA expression has been demonstrated in malaria vaccinated adults; however, the authors concluded that this might be attributed to the participants being naturally exposed to the malaria parasite rather than as a result of vaccination per se." (PMID 25309517, 2014). "Although not significant, we observed a reduced frequency of CD4+C25+FoxP3+ expressing Ki-67 and CTLA-4 among patients with a previous malaria exposure." (PMID 40726977, 2025). "Flow cytometric analysis showed that the majority of PD1+CTLA4+CD4+ T cells in malaria patients were Foxp3- and CD25-, which indicates that they were not Foxp3+ natural Tregs (nTregs)." (PMID 27802341, 2016). "In line with this, Walther and co-workers recently also found a correlation between Foxp3 and TNFRII levels on Tregs from malaria infected children, and Minigo and colleagues reported higher levels of TNFRII expression on Tregs from individuals with severe as opposed to uncomplicated malaria." (PMID 19680449, 2009).
viral infection (54 papers, 2007 to 2025). "To address the possible role of virus infections in the modulation of FOXP3 in Tregs, we analyzed the temporal association of virus infection with the expression of FOXP3 in Tregs." (PMID 33643278, 2020). "We show here a temporal association of virus infection with the expression of FOXP3 in regulatory T cells." (PMID 33643278, 2020). "Frequency of polymorphisms in the FOXP3 gene promoter region according to the histopathological characteristics of patients with chronic hepatitis B and C virus infections." (PMID 30233595, 2018). "Genotype and allele polymorphism frequencies in the FOXP3 gene promoter region in patients with chronic hepatitis B and C virus infections." (PMID 30233595, 2018). "Haplotype frequencies of polymorphisms of the FOXP3 gene promoter region (−924A>G,−2383C>T, and −3279C>A) in patients with chronic hepatitis B and C virus infections." (PMID 30233595, 2018). "We speculate that the loss of Foxp3-depleted Treg cells in settings of autoimmune inflammation, viral infection, or cancer may result from their exposure to a complex combination of these stimuli." (PMID 40478934, 2025). "On the other hand, FoxP3+ Treg cells could prevent tissue damage caused by excessive immune response triggered by viral infection." (PMID 22647666, 2012). "We next asked if TH1-like TREG cells generated during an acute viral infection were similarly dependent on Foxp3." (PMID 40478934, 2025). "Conversely, TREG cells that were activated in response to autoimmune-inflammation, viral infection, cancer, or adoptive transfer into lymphopenic hosts were acutely dependent on Foxp3 for their maintenance." (PMID 40478934, 2025). "CD8+Foxp3+ T cells have been reported to play a role in several pathological and physiological processes, including cell death, necrosis, and apoptosis; viral infection; and immune cell proliferation." (PMID 39136032, 2024). "CD4+/CD25+FoxP3+ regulatory T cells (Tregs) play an important role in the immune response to viral infections and especially in the balance between immunity and tolerance." (PMID 38979428, 2024). "In contrast, other reports indicate STAT1 and type I IFN induced during viral infections inhibit Treg cell proliferation and activation of Foxp3+ Tregs." (PMID 38085267, 2024). "In recent years, there has been an increasing number of studies on CD4+/CD25+FoxP3+ regulatory T cells (Tregs) and their involvement in viral infections." (PMID 38979428, 2024). "Robust type I IFN synthesis during viral infections inhibits Treg activation and proliferation, but a complete loss of type I IFN signaling in Tregs impairs Treg FoxP3 expression and suppressor function." (PMID 36512407, 2023). "CD25+Foxp3+CD4+ regulatory T cells (Tregs) have an important inhibitory effect during viral infection." (PMID 37773701, 2023). "If the suppressive function of FOXP3+ Tregs is too strong at the early stage of virus infection, the immune response of host will be suppressed by Tregs and cannot produce an adequate immune response for viral clearance." (PMID 35874688, 2022). "While this assumption is generally valid for acute viral infections, there are some notable differences, particularly in FoxP3 and CD4 expression levels." (PMID 34944938, 2021). "High levels of FoxP3+CD4+ T cells are present in the CNS of virus-infected mice as early as 3 d after viral infection." (PMID 34067536, 2021). "TMEV-infected mice treated with ex vivo-generated FoxP3+ Tregs at an early stage of viral infection worsened the clinical signs, whereas the mice treated with the Tregs at a later stage decreased immune cell recruitment in the CNS." (PMID 34067536, 2021). "High levels of FoxP3+CD4+ T cells were found in the CNS early in viral infection (3 dpi) and persisted throughout the infection." (PMID 33086489, 2020).
viral infection (continued). "Our finding of the up-regulation of FOXP3 expression in Treg cells after rhinovirus infections is in line with studies showing activation of Treg cells in the context of virus infection." (PMID 33643278, 2020). "Irrespective of the overall common suppressive action in draining LN during viral infection, the function of endogenous Foxp3+ Treg migrating to and residing in the CNS throughout persistence remains obscure." (PMID 27708643, 2016). "In this study, we investigated the role of Foxp3+ Tregs during an acute viral infection in the CNS using DEREG mice in which Tregs can be selectively depleted by injecting DT." (PMID 25391297, 2014). "We examined the role of Foxp3+ Treg cell responses in chronic viral infections in mice infected with the fast-replicating strain of LCMV-DOC." (PMID 23696736, 2013). "The morphologic similarities of the expanded HEVs in the Foxp3-DTR mice with that after acute OVA/CFA immunization or viral infection suggests the possibility of at least some shared regulatory mechanisms." (PMID 22973277, 2012). "Thus, in contrast to resting TREG cells residing in healthy organs of unperturbed mice, TREG cells actively responding to autoimmune inflammation and viral infection are continuously dependent on high levels of Foxp3 protein." (PMID 40478934, 2025). "To determine when after viral infection FOXP3+ Tregs promote recovery and optimize the timing of Treg adoptive transfer, we first assessed whether the timing of Treg renewal determines influenza pneumonia recovery phenotypes." (PMID 40956625, 2025). "The results indicate that variations in the FOXP3 gene may play a role in histopathological sequelae observed in the liver following viral infection." (PMID 39117877, 2024). "In contrast, FoxP3+CD4+ T cells may be beneficial in controlling prolonged T cell responses in acute viral infections." (PMID 33086489, 2020). "Therefore, the first cell type accumulated at the site of viral infection appears to be FoxP3+CD4+ T cells." (PMID 33086489, 2020). "Moreover, CD4+CD25+Foxp3+Treg cells contribute to the adaptive and innate immune responses during acute viral infection." (PMID 28265274, 2017). "The role of CD4+CD25+Foxp3+ in acute viral disease is still controversial." (PMID 28265274, 2017). "As hepatitis B/C virus infection are the principal causes of HCC in China1, we further compared FOXP3 expression in CD3+CD56+ cells in HCC patients with or without a history of viral infection." (PMID 26437631, 2015). "The role of CD4+CD25+Foxp3+ Tregs in acute viral diseases is still debatable." (PMID 25188232, 2014). "Moreover, since CD4+CD25+Foxp3+ Treg cells contribute to the dampening of innate and adaptive immune responses during acute viral infection, we addressed the frequency and number of CD4+CD25+Foxp3+ Treg cells in the spleen." (PMID 25188232, 2014). "In addition to conventional T cells, Mtv has been shown to modulate the population of Foxp3+ regulatory T cells via a Sag-dependent manner during the course of chronic viral infection." (PMID 24324930, 2013). "In addition to modulation of the conventional population of CD8+ and CD4+ T cells, Mtv have been demonstrated to influence the immune system during viral infection via expansion of a particular subset of CD4+ T cells expressing the transcription factor Foxp3." (PMID 24324930, 2013). "First, FoxP3+ T cells are known to contact with dendritic cells (DCs) frequently, which could increase the chance of de novo viral infection between DCs and FoxP3+ T cells." (PMID 22647666, 2012). "A recent study also demonstrated that the Foxp3+ Treg cells could facilitate early immune responses to local viral infection at least in part by orchestrating a timely homing of immune effector cells to the site of infection." (PMID 20064222, 2010). "Furthermore, the dual roles of FOXP3+ Tregs during viral infection should be reminded." (PMID 35874688, 2022).
viral infection (continued). "Two types of FOXP3+ Tregs could affect the immunopathogenesis during viral infections." (PMID 34956200, 2021). "In contrast, FoxP3+CD4+ T cells may be beneficial in controlling acute viral infections." (PMID 34067536, 2021). "In addition, FOXP3 increases the inhibitory effect of Tregs on the immune system and promotes an incomplete immune response to the virus, ultimately resulting in a chronic viral infection." (PMID 24944616, 2014). "Taken together, although the precise mechanisms of CD25+ Foxp3 Tregs function still remain to be identified for many herpes virus infections, these cells represent an important regulatory subtype that strongly impacts the virus/host balance during persistent virus infections." (PMID 23717308, 2013). "Next, we highlight an underappreciated branch of immunological research on Human T-cell Leukemia Virus type 1 (HTLV-1) that precedes Treg studies, illuminating the missing link between the viral infection, CD25, and Foxp3." (PMID 38863793, 2024). "In many chronic viral infections, including TMEV, FoxP3+CD4+ T cells appear to contribute to the pathogenesis by inhibiting protective T cell function and consequently promoting viral persistence." (PMID 34067536, 2021). "The differential genes such as KITLG, FOXP3, miR-451, IL-2, IL-10, IL-6, and TNF-α are mainly involved in viral infection and the immune-inflammatory responses." (PMID 34867371, 2021). "In many chronic viral infections, including TMEV, FoxP3+CD4+ T cells appear to contribute to the pathogenesis by inhibiting protective T cell functions and consequently promoting viral persistence." (PMID 33086489, 2020). "The reports that IL-2 can expand and induce Treg cells in vivo and in vitro, are in line with our present study showing that depletion of FoxP3-expressing cells blocked CNS demyelination by HSV-IL-2 and required both IL-2 and viral infection." (PMID 28542613, 2017). "Virus infection induced GATA-3 expression and Th2 cytokine production in forkhead box P3 (FOXP3)+ Treg cells and compromised the suppressive function of pulmonary Treg cells." (PMID 23986756, 2013). "T13, the Tregs (CD25+FOXP3+CD45RO+CD4+), is essential to maintain immune homeostasis via governing aggravated and destructive inflammation, exhibiting protective roles in the host during viral infections." (PMID 35720399, 2022). "In the absence of ex vivo stimulation, IL-2 production by naive Foxp3− CD4+ T cells was also observed in early life after viral infection, and IL-2+ cells expressed more IL-2 per cell than those from adults." (PMID 34665220, 2021). "Distinct from reports of virus infection, we found that IL-10 was expressed by conventional, Foxp3-negative effector CD4 T cells and functioned in a B cell-intrinsic manner only during the first 96 hours of Plasmodium infection to support humoral immunity." (PMID 33529242, 2021). "The most down-modulated genes were related to T helper 2 pathway activation and induction of FOXP3 expression (AREG), immune tolerance (SMAD6), response to bacterial and viral infection and inflammation (CXCL8, PDE12, STX19, DFNB31), cell transport of glucose and organelles (KIF5A, SCL2A7)." (PMID 35058920, 2021). "The children who had had at least one virus infection during the preceding 30 or 60 days showed increased expression of FOXP3 in Tregs in comparison to the children without virus infections in the same time period (p = 0.005 and p = 0.124)." (PMID 33643278, 2020). "The current study shows that exposure to AvCystatin leads to enhanced recruitment of IL-10-producing CD4+ T cells in viral infection; however, FoxP3 expression did not coincide with IL-10 production in the regional lymph nodes." (PMID 27560829, 2016). "Surprisingly, HIV infection dramatically increased Foxp3 expression in TCR-stimulated CD25- T cells compared to those without virus infection (58% vs. 18%)." (PMID 17688698, 2007).
viral infection (continued). "Accordingly, FOXP3 regulates Treg cell function and may suppress antiviral immune responses; moreover, its increased expression in some chronic HCV patients may contribute to a reduced ability to control the viral infection and resistance to DAAs treatment." (PMID 39117877, 2024). "In addition, downregulation of the FOXP3 gene was significant in RR‐MS patients recently affected by viral infections compared to MS patients with no history of infection (p < 0.03)." (PMID 35266286, 2022). "In this study, using the well-established technique of in-vivo Foxp3+ cell ablation by administration of DTx to Foxp3-DTR animals, we first assessed the presence of Tregs within the brains of both DTx-treated and untreated animals from acute through chronic phases of viral infection." (PMID 26720146, 2015). "It is well known that not all human Foxp3+ cells are Treg, particularly under conditions of chronic cell activation, such as a viral infection, where there may be a higher proportion of effector T cells that transiently upregulate Foxp3." (PMID 24155942, 2013). "The purpose of this study was to elucidate whether the expression of Foxp3 relates not to the viral infection but to the resulting liver inflammation." (PMID 21772667, 2011). "Foxp3+ CD4+ regulatory T cells represent a T cell subset with well-characterized immunosuppressive effects during immune homeostasis and chronic infections, and there is emerging evidence to suggest these cells temper pulmonary inflammation in response to acute viral infection." (PMID 22125630, 2011).